INS (insulin)
Diseases named in the same sentence as INS in open-access papers (continued):
Sharing a sentence is not in itself a finding about the gene and the disease.
gestational diabetes (continued). "Gestational diabetes is a condition characterized by impaired insulin action caused by hormones produced by the placenta, resulting in elevated blood sugar levels." (PMID 37724233, 2023). "Gestational diabetes is caused by a deficit in insulin production in the pregnant woman, whose pancreas is unable to generate the insulin necessary to meet the insulin requirements of pregnancy." (PMID 38202044, 2023). "This study aimed to use routinely collected data to identify risk factors associated with insulin need in women with gestational diabetes and to develop an easy-to-use application to estimate the probability of insulin need." (PMID 37268897, 2023). "The ADA recommends that women with gestational diabetes have access an individualized nutrition plan to avoid the complications caused by insulin resistance." (PMID 37799768, 2023). "Gestational diabetes (diagnosed for the first-time during pregnancy) occurs more frequently in overweight, hyper-insulinemic, insulin-resistant or lean insulin-deficient women." (PMID 36670995, 2023). "Whalen and Taylor indicated that gestational diabetes is caused by hormonal changes that occur in the body during pregnancy, which causes insulin resistance." (PMID 37109521, 2023). "Gestational diabetes is thought to be caused by the inability of the pancreas to produce insulin to handle excess sugar load during pregnancy." (PMID 36909346, 2023). "In contrary, DNAm GA deceleration of the offspring at birth was associated with insulin-treated gestational diabetes mellitus (GDM) in a previous pregnancy and Sjögren’s syndrome." (PMID 37520545, 2023). "Hummel found decreased duration of breastfeeding in gestational diabetes was independently associated with insulin treatment (versus diet manipulation)." (PMID 35405936, 2022). "Are glyburide and subcutaneous insulin use associated with different rates of perinatal complications among individuals with gestational diabetes?" (PMID 35357451, 2022). "Prenatal care coverage was associated with a 10.4-percentage-point increase in insulin use (95% CI, 5.3-15.5 percentage points) among individuals with gestational diabetes." (PMID 35486400, 2022). "This cohort study compares the perinatal outcomes associated with initiating glyburide vs insulin among individuals with gestational diabetes." (PMID 35357451, 2022). "Gestational diabetes is associated with neonatal polycythemia, possibly due to elevated insulin and erythropoietin." (PMID 35232426, 2022). "Myo-inositol (MI) supplementation of 4 g per day greatly reduced gestational diabetes (GD) in at risk women, and reduced insulin and fasting blood glucose in women with GD." (PMID 35818085, 2022). "The aim of this study was to find potential risk factors for insulin dependency and treatment requirements using information available at the time of diagnosis of gestational diabetes during pregnancy." (PMID 34640439, 2021). "This study aimed to compare a 75-g oral glucose tolerance test and a 500-kcal meal tolerance test (MTT) to identify factors predicting high-risk patients with gestational diabetes mellitus (GDM) who need insulin therapy." (PMID 33776619, 2021). "Overall, low chromium is associated with gestational diabetes, and chromium supplementation improves glucose and insulin levels." (PMID 34071548, 2021). "Women with gestational diabetes during the second and third trimesters are susceptible to ketosis due to increased insulin resistance and FFAs, which further enhance AT lipolysis as well as the hepatic ketogenesis process." (PMID 34835958, 2021). "We have previously reported associations of insulin-treated pregestational diabetes and gestational diabetes with some of the offspring psychiatric and neurodevelopmental disorders in this cohort, but we used a different reference group." (PMID 32031649, 2020).
gestational diabetes (continued). "Our studies showed that insulin treatment significantly increased the number of newborn mice, and lowered blood glucose levels, indicating that insulin can rescue the abnormal development in newborn mice caused by STZ-induced gestational diabetes." (PMID 30973884, 2019). "All these risk factors were integrated in a further multivariable analysis (except for insulin intake since it is strongly associated to gestational diabetes), and they all remained significant." (PMID 31731659, 2019). "In the present study, insulin treatment of gestational diabetes was associated with improvement of placental vascular circulation but not pregnancy complications." (PMID 30873116, 2019). "Regarding the global increment in gestational diabetes, determination of high-risk populations requiring insulin therapy is crucial." (PMID 31656196, 2019). "Pathophysiology of gestational diabetes mellitus: Gestational diabetes mellitus is caused by a disorder of at least three aspects of metabolism: insulin resistance, insulin secretion and increased glucose production." (PMID 30820209, 2018). "Gestational diabetes mellitus is associated with an altered maternal environment, which includes changes in circulating adipokines, growth hormones, and insulin, all of which can influence placental development and function." (PMID 29163373, 2017). "Pregnancy-associated plasma protein A concentrations, measured at the start of the second trimester, were associated with subsequent insulin sensitivity, blood pressure, and gestational diabetes." (PMID 28323969, 2017). "Metformin is often preferred especially for correcting insulin insensitivity, promoting weight loss while reducing the risk of gestational diabetes and inducing spontaneous ovulation." (PMID 25990477, 2015). "Gestational diabetes mellitus is a group of diseases that result from deficiencies in insulin action and/or insulin secretion." (PMID 16612455, 2006). "During normal pregnancy, placental exosome release increases progressively; however, gestational diabetes mellitus is associated with a further elevation in circulating placental exosomes enriched in bioactive cargo linked to inflammation, glucose metabolism, and insulin signaling." (PMID 41516185, 2025). "The distinction identified in this study between EFG and EPG may align with emerging recognition of gestational diabetes subtypes, most notably insulin-resistant (IRGD) versus insulin-deficient (IDGD) subtypes." (PMID 39940258, 2025). "However, pregnant women after RYGB had lower risk of gestational diabetes and better insulin sensitivity compared to control subjects." (PMID 39203840, 2024). "We might need a larger sample size to confirm that controlling gestational diabetes with insulin could significantly decrease the risk of cryptorchidism." (PMID 39439600, 2024). "The strengths of this study include the measurement of maternal Vitamin D status and insulin levels during the critical period; our study provides important insights into the association between these factors and gestational diabetes among women visiting government hospitals for antenatal care." (PMID 38887504, 2024). "Numerous studies suggest that low-carbohydrate diets (LCDs) may have benefits during pregnancy, including lowering blood sugar, improving insulin resistance, and reducing the risk of gestational diabetes." (PMID 39064712, 2024). "Studies on both humans and rodents show that treatment with MI during pregnancy significantly improves the alterations associated with gestational diabetes, leading to a reduction in the number of pregnant women requiring insulin treatment and ameliorating their fetus’s development." (PMID 38613013, 2024). "As described, genetic variation, through its effect on gene expression and, ultimately, islet cell mass and function and insulin sensitivity, is associated with risks for both gestational diabetes and T2DM, with an overlap of the genetic variants associated with these two disorders." (PMID 37047019, 2023).
gestational diabetes (continued). "There is evidence suggesting that genetic variants may play a role in the development of gestational diabetes by affecting insulin resistance, beta-cell function, and inflammation." (PMID 37724233, 2023). "Physical activity, in addition to its cardiac benefits and its association with higher vaginal birth rates, increases non-insulin glucose uptake in muscles bypassing the physiologic insulin resistance of pregnancy and lowering the risk for gestational diabetes." (PMID 38276803, 2023). "Healthcare professionals can utilize this new prediction tool to identify patients who are at a higher risk of developing insulin dependency and tailor their management and treatment plans accordingly to optimize maternal and fetal outcomes in gestational diabetes cases." (PMID 38002781, 2023). "However, when underlying β-cell dysfunction and impaired insulin secretion are present, the mother cannot maintain glucose homeostasis and gestational diabetes mellitus (GDM) results." (PMID 37240215, 2023). "One possible mechanism is that gestational diabetes and maternal overweight is related to the abnormal oxidative stress, energy homeostasis, angiogenesis and insulin insensitivity, which are all tightly associated with negative consequences for both mother and her fetus." (PMID 37893486, 2023). "During pregnancy, the increase in maternal insulin resistance is compensated by hyperplasia and increased function of maternal pancreatic beta cells; the failure of this compensatory mechanism is associated with gestational diabetes mellitus (GDM)." (PMID 37480094, 2023). "Collectively, these data support the hypothesis that humanin and MOTSc may be involved in changes in insulin sensitivity that arise from the early stages of pregnancy and the risk of gestational diabetes." (PMID 35683389, 2022). "Pregnancy is characterized by a physiological increase in insulin resistance which, in predisposed women, could induce alterations in glucose metabolism and gestational diabetes mellitus (GDM)." (PMID 35458105, 2022). "However, future studies of ganglioside supplementation during pregnancy should assess the effects on glucose tolerance, insulin sensitivity, and gestational diabetes risk." (PMID 33626041, 2021). "In addition, treatment of gestational diabetes with diet or insulin was associated with lower risk of macrosomia in a meta-analysis of four randomized controlled trials from developed countries." (PMID 33224106, 2020). "As shown in studies, myoinositol may reduce the risk of developing gestational diabetes mellitus by improving insulin sensitivity." (PMID 31886278, 2019). "The present study demonstrates for the first time that postpartum circulating cell-free insulin DNA levels are significantly higher in women with gestational diabetes and could be used to stratify those at risk of progressing to T2DM in later life." (PMID 31428654, 2019). "Gestational diabetes, which affects an estimated 18 percent of women during pregnancy, is caused by a change in the way a woman's body responds to insulin during pregnancy could be a major risk factor for the development of T2DM." (PMID 30042922, 2018). "The aim of this cross-sectional analysis was to investigate whether insulin resistant women with previous gestational diabetes (pGDM), a high risk group for T2D, differ in their stool microbiota from women after a normoglycemic pregnancy (controls)." (PMID 26279179, 2015). "We could not differentiate whether the low cord plasma DHA levels observed in gestational diabetes are a cause or consequence of impaired fetal insulin sensitivity in gestational diabetes." (PMID 24454790, 2014). "Because both MO and gestational diabetes have been associated with decreased insulin sensitivity and increased IR status in the offspring, we will analyze how those insulin signaling mechanisms could be impaired in pregnancy." (PMID 25093191, 2014).
gestational diabetes (continued). "Obese women are more insulin resistant than their normal weight counterparts, both before and during pregnancy and this is associated with an increased risk of developing gestational diabetes mellitus (GDM) and of giving birth to a large baby with increased fat mass." (PMID 24386400, 2013). "In women with familial partial lipodystrophies, decreased fertility and obstetrical complications have been reported to be mainly linked to insulin resistance and metabolic disturbances, with an increased prevalence of polycystic ovary syndrome, gestational diabetes and eclampsia." (PMID 23849162, 2013). "In FitFor2-study we aim to assess whether an exercise program can improve insulin sensitivity and fasting plasma glucose levels of women at high risk for gestational diabetes, assuming that this will lower their risk of gestational diabetes." (PMID 19123930, 2009). "The overall aim of the FitFor2 study is to assess whether an exercise program can improve insulin sensitivity and fasting plasma glucose levels of women at high risk for gestational diabetes, assuming that this will lower their risk of GDM." (PMID 19123930, 2009). "Conversely, maternal obesity and gestational diabetes mellitus (GDM) expose the unborn to surplus glucose and insulin in utero, predisposing them to obesity and type 2 diabetes." (PMID 41141052, 2025). "Chronic maternal stress during pregnancy is linked with decreased insulin sensitivity of the mother, and it was also identified as a potential risk factor for gestational diabetes mellitus (GDM)." (PMID 41303554, 2025). "In this work, DNAm GA deceleration of the offspring at birth was associated with insulin-treated gestational diabetes mellitus (GDM) in a previous pregnancy and Sjögren’s syndrome." (PMID 37520545, 2023). "Impaired glucose metabolism and insulin sensitivity have been linked to the pathogenesis of gestational diabetes mellitus (GDM)." (PMID 35726320, 2022). "Compared to insulin and Glibenclamide therapies, macrosomia, or large for gestational age births, newborn hypoglycemia, and admission of the infant to neonatal intensive care units are all at a decreased risk when metformin medication is used to treat gestational diabetes mellitus." (PMID 36381747, 2022). "The inability to compensate for the increased demand for insulin during pregnancy underlies the pathophysiological mechanisms of gestational diabetes mellitus (GDM)." (PMID 34946940, 2021). "Interestingly, maternal gestational diabetes mellitus (GDM) has been associated with defective insulin signaling within the placenta and increased vascularization, leading us to hypothesize that Plagl1 could be misexpressed in GDM placentas." (PMID 33171905, 2020). "A pregnancy-related 60% decrease in insulin sensitivity puts overweight and obese women at greater risk for complications such as gestational diabetes mellitus (GDM), preeclampsia, and fetal growth abnormalities." (PMID 32455565, 2020). "Gestational diabetes mellitus (GDM) is a pregnancy-related complication defined as glucose intolerance associated to maternal decreased insulin sensitivity and increased insulin resistance." (PMID 28655969, 2017). "DNAm GA deceleration (GAD; i.e., younger DNAm GA than chronological GA) of the offspring at birth was associated with insulin-treated gestational diabetes mellitus (GDM) in a previous pregnancy and Sjögren’s syndrome." (PMID 28503212, 2017). "Since no biomarkers exist to reliably identify at-risk subjects at this age we chose insulin resistant women with a recent history of gestational diabetes (GDM) as our high risk cohort and compared these to a suitable control group." (PMID 26279179, 2015). "Gestational diabetes mellitus (GDM) is a condition typically caused by insufficient insulin production or signaling in pregnant women." (PMID 26542478, 2015). "Insulin is commonly used to decrease many of the diabetes-associated complications in gestational diabetes mellitus (GDM)." (PMID 25541979, 2014).
gestational diabetes (continued). "This study was undertaken to assess the association between insulin need in gestational diabetes mellitus (GDM) and clinical features and laboratory parameters." (PMID 23976911, 2013). "No studies so far have investigated the association between Lp(a) and insulin sensitivity parameters in gestational diabetes mellitus (GDM)." (PMID 24083682, 2013). "In a streptozotocin (STZ)-induced gestational diabetes model, betaine significantly increased insulin levels, restored normal plasma total homocysteine concentrations, and enhanced insulin resistance and blood lipid status." (PMID 41608511, 2026). "Her pregnancy was complicated by insulin-requiring gestational diabetes and late-onset pre-eclampsia." (PMID 41909318, 2026). "Gestational diabetes mellitus (GDM) is a pregnancy-specific metabolic disorder characterized by impaired glucose regulation due to heightened insulin resistance and insufficient pancreatic β-cell compensation." (PMID 41596503, 2026). "In a gestational diabetes model, behenic acid feeding prevents glucose and insulin metabolism defects, abnormal weight gain, and offspring mortality." (PMID 40573128, 2025). "In women with diet-controlled gestational diabetes, a centrally decreased insulin secretion already appears in the postprandial phase, indicating a dysfunction of ß-cells in this group." (PMID 39384641, 2025). "Given the high and increasing international prevalence for gestational diabetes, this is an important finding as reducing or delaying the initiation of insulin therapy has financial benefits by reduction in medication cost and staff time." (PMID 39473074, 2025). "Complementary transcriptomic analyses have revealed altered gene expression profiles in HUVECs derived from women with gestational diabetes mellitus (GDM), particularly in pathways associated with metabolism, inflammation, oxidative stress, and insulin signaling." (PMID 41020807, 2025). "In this study, we distinguished between insulin-treated and diet-controlled gestational diabetes mothers and compared them to a normoglycemic control group." (PMID 39384641, 2025). "This is a secondary analysis of a previous trial in which women with newly diagnosed gestational diabetes were randomized to metformin versus insulin treatment." (PMID 40544417, 2025). "Gestational diabetes mellitus (GDM) is a complex metabolic condition that arises from the interaction between insulin resistance and insufficient pancreatic β-cell compensation during pregnancy." (PMID 40722699, 2025). "The examined fetal blood of the normoglycemic control as well as the diet-controlled gestational diabetes patients showed significantly lower arterial insulin levels compared to the venous (maternal) serum." (PMID 39384641, 2025). "Based on these results, we can say that the carbohydrate metabolism of obese women is more altered, leading to a higher incidence of gestational diabetes requiring more intensive treatment, including diet, lifestyle changes, and insulin treatment." (PMID 39859033, 2025). "The results of this study confirmed an impaired vasorelaxation in fetal placental vessels from women with insulin-treated gestational diabetes compared to normoglycemic controls." (PMID 39384641, 2025). "Analyses of blood serum from umbilical cords suggested a reduced fetal insulin metabolism in the insulin-treated gestational diabetes group." (PMID 39384641, 2025). "The lowest TAC levels were observed in mothers with insulin-treated gestational diabetes (GDM G2), followed by the diet-controlled GDM group (GDM G1), with the highest levels found in the control group." (PMID 41228398, 2025). "Optimizing metabolic health prior to and during pregnancy—through interventions aimed at improving insulin sensitivity and controlling gestational diabetes—can help restore the anabolic signaling pathways essential for mammary gland function." (PMID 40868103, 2025).